NEU4 (neuraminidase 4)
Description:
Exo-alpha-sialidase that catalyzes the hydrolytic cleavage of the terminal sialic acid (N-acetylneuraminic acid, Neu5Ac) of a glycan moiety in the catabolism of glycolipids, glycoproteins and oligosaccharides. Efficiently hydrolyzes gangliosides including alpha- (2->3)-sialylated GD1a and GM3 and alpha-(2->8)-sialylated GD3. Hydrolyzes poly-alpha-(2->8)-sialylated neural cell adhesion molecule NCAM1 likely at growth cones, suppressing neurite outgrowth in hippocampal neurons (By similarity). May desialylate sialyl Lewis A and X antigens at the cell surface, down-regulating these glycan epitopes recognized by SELE/E selectin in the initiation of cell adhesion and extravasation. Has sialidase activity toward mucin, fetuin and sialyllactose.
Tractability: Small molecule: a high-quality ligand is known. Antibody: UniProt places it where antibodies can reach, with high confidence; its Gene Ontology location is reachable by antibodies, with medium confidence. PROTAC: a small molecule that binds it is known.
Target class: Enzyme; Hydrolase
Gene: Protein-coding gene on chromosome 2 (241,808,982 to 241,817,415, forward strand). Ensembl gene ENSG00000204099.
Subcellular location: Cell membrane (Isoform 1); Endoplasmic reticulum membrane; Microsome membrane; Mitochondrion membrane; Cell projection, neuron projection; Mitochondrion inner membrane (Isoform 2); Mitochondrion outer membrane; Lysosome lumen
Pathways (Reactome):
Metabolism: Glycosphingolipid catabolism
Metabolism of proteins: Sialic acid metabolism
Gene Ontology:
Molecular function: exo-alpha-sialidase activity; protein binding
Biological process: ganglioside catabolic process; glycoprotein catabolic process; oligosaccharide catabolic process; negative regulation of neuron projection development
Cellular component: endoplasmic reticulum membrane; lysosomal lumen; lysosome; mitochondrial inner membrane; mitochondrial membrane; mitochondrial outer membrane; organelle inner membrane; plasma membrane; cytoplasm; membrane; neuron projection
Genetic constraint (gnomAD): Loss-of-function variants: 7 observed, 8.41 expected, observed/expected ratio (o/e) 0.83, 90% interval 0.47 to 1.54. That is too few expected variants to judge how well the gene tolerates losing a copy. Missense variants: 717 observed, 652.8 expected, observed/expected ratio (o/e) 1.1, 90% interval 1.03 to 1.17. Synonymous variants: 348 observed, 292.52 expected, observed/expected ratio (o/e) 1.19, 90% interval 1.09 to 1.3.
Homologues: Orthologues: chimpanzee NEU4 (99% identical), macaque NEU4 (95% identical), pig NEU4 (77% identical), dog NEU4 (73% identical), mouse Neu4 (71% identical), rat Neu4 (70% identical), guinea pig NEU4 (70% identical), tropical clawed frog neu4 (45% identical), zebrafish neu4 (43% identical). Paralogues in human: NEU3 (38% identical), NEU2 (35% identical), NEU1 (21% identical).
Diseases named in the same sentence as NEU4 in open-access papers:
NEU4 is named in the same sentence as 31 diseases in open-access papers, as found by Europe PMC text mining. Sharing a sentence is not in itself a finding about the gene and the disease. The quoted sentences say what the papers report.
colon cancer (4 papers, 2016 to 2021). "NEU3 is a degradation enzyme for sialyl Lewis X but not for sialyl Lewis A8, but NEU3 is expressed at much lower levels relative to NEU4 in all colon cancer cells." (PMID 30700826, 2019). "NEU4, another down-regulated gene, maintains normal mucosa and its down-regulation was suggested to contribute to invasive properties of colon cancers." (PMID 29284484, 2017). "Neu4 is highly expressed in the mucosal surfaces of the colon, although this expression was markedly reduced in colon cancer, suggesting a protective role for Neu4 in the maintenance of normal colon mucosa." (PMID 27029067, 2016). "NEU4 expression is reduced in colon cancer patients, and its expression may be related to cancer cell apoptosis." (PMID 30700826, 2019). "Here we showed that p73 activates the NEU4 short form in colon cancer cells." (PMID 30700826, 2019). "We propose that p73 and AP2 synergistically activate the NEU4 promoter in colon cancer cells." (PMID 30700826, 2019). "NEU4 was down-regulated in all EMT-induced cancer stem-like cells colon cancer cell lines DLD1, HT29 and LS174T, but not NEU1, NEU2 and NEU3." (PMID 30700826, 2019). "Previous study indicates that NEU4 desialylates cell surface sLeA/X to LeA/X without affecting the expression of ST3GAL3, ST3GAL4, FUT3, and FUT7 in colon cancer cells." (PMID 34135905, 2021).
neuroblastoma (3 papers, 2016 to 2022). Neuroblastoma (NB) is the most common solid, extracranial childhood tumor. "The report provided strong evidence to demonstrate that Neu4 overexpression is associated with an upregulation of stem cell-like properties in neuroblastoma cells." (PMID 27608845, 2016). "Overexpression of NEU4 in ST8SiaIV-transfected neuroblastoma Neuro2a cells decreased PSA levels whereas silencing the endogenous Neu4 in mouse embryonic hippocampal primary neurons increased both the PSA levels on neurites and their outgrowth." (PMID 30088207, 2018). "Notably, NEU4 has been identified as a potential regulator of neuronal development, with overexpression promoting the acquisition of a stem cell-like phenotype in neuroblastoma cells." (PMID 36605200, 2022).
atherosclerosis (2 papers, 2021 to 2022). A disease characterized by the build-up of fatty material and calcium deposition in the arterial wall resulting in partial or complete occlusion of the arterial lumen. "In this study, NEU1-deficient (CathAS190A‐Neo), Neu3−/− or Neu4−/− mice were crossed with Apoe−/− mice, and atherosclerosis was evaluated." (PMID 36157440, 2022). "In contrast, the progression of atherosclerosis in Neu4(-/-) Apoe(-/-) mice was not significantly different, compared to Apoe(-/-) animals with normal Neu4 activity." (PMID 34070542, 2021).
glioma (2 papers, 2023 to 2025). A benign or malignant brain and spinal cord tumor that arises from glial cells (astrocytes, oligodendrocytes, ependymal cells). "Moreover, NEU4 and GPR17 expression was enriched in the tumor cell clusters of both sporadic and NF1-associated low-grade gliomas (pilocytic astrocytoma)." (PMID 41497446, 2025). "HBS-101, a novel midkine inhibitor, reduced optic nerve proliferation, normalized RNFL thickness, and decreased the expression of tumor (Neu4, Gpr17) and TME (Ccl2, Ccl3, Ccl4, Ccl5) genes, supporting its continued development as a targeted therapy for pediatric NF1-associated glioma." (PMID 41497446, 2025).
lysosomal storage disease (2 papers, 2018 to 2024). A metabolic disorder caused by mutations in proteins critical for lysosomal function, including lysosomal enzymes, lysosomal integral membrane proteins, and proteins involved in the post-translational modification and trafficking of lysosomal proteins. "NEU4 encodes a sialidase which has been implicated in cancer, lysosomal storage disease, neurogenesis and apoptosis and intriguingly, methylation at this region has been associated with prenatal events." (PMID 39217505, 2024). "Hence these cells follow the conventional theme of a lysosomal storage disease for the neu3-/-neu4-/- mouse model." (PMID 30359429, 2018).
chronic kidney disease (1 paper, 2024). Impairment of the renal function secondary to chronic kidney damage persisting for three or more months. "In conclusion, this study identifies a promotor role for NEU4 in renal fibrosis and proposes a potential therapeutic strategy involving the targeting NEU4 for the treatment of chronic kidney disease." (PMID 39136142, 2024). "Of these, the role of NEU4 in diseases, especially chronic kidney disease, however, remain largely unexplored." (PMID 39136142, 2024).
glioblastoma (1 paper, 2016). The most malignant astrocytic tumor (WHO grade IV). "al demonstrated that glioblastoma stem cells (GSC), isolated from patients and multiforme cell lines, are associated with an upregulation of Neu4 activity." (PMID 27608845, 2016).
GM1 gangliosidosis (1 paper, 2018). A rare lysosomal storage disorder characterized biochemically by deficient beta-galactosidase activity and clinically by a wide range of variable neurovisceral, ophthalmological and dysmorphic features. "However, the Neu4 and Neu3 KO mouse models do not develop massive lysosomal storage of any ganglioside or severe clinical phenotypes resembling those of the Glb1 KO mouse (model of GM1 gangliosidosis) or β-hexosaminidase deficient Hexb KO mouse (model of Sandhoff disease)." (PMID 30088207, 2018).
GM2 gangliosidosis (1 paper, 2023). A group of recessively inherited diseases characterized by the intralysosomal accumulation of G(M2) GANGLIOSIDE in the neuronal cells. "Additionally, it is possible that in the absence of NEU3, both NEU4 and NEU1 may partially compensate for this sialidase loss, as all neuraminidase activity has been shown to be increased in mouse models of GM2 gangliosidosis." (PMID 38098938, 2023).
metastatic disease (1 paper, 2016). "The potential clinical implications of these studies suggest that selectively targeting Neu4 and Neu1 could modify the glycosylation state of cell surface proteins, thus reducing tumor growth and preventing metastatic disease." (PMID 27608845, 2016).
renal fibrosis (1 paper, 2024). A final common manifestation of a wide variety of chronic kidney diseases characterized by glomerulosclerosis and tubulointerstitial fibrosis. "To investigate the underlying mechanism by which NEU4 promotes renal fibrosis, we performed immunoprecipitation combined with mass spectrometry analysis (IP‐MS) in protein lysates of TGF‐β‐induced HK‐2 cells." (PMID 39136142, 2024). "Co‐immunoprecipitation and liquid chromatography‐tandem mass spectrometry, bimolecular fluorescence complementation (BiFC), and surface plasmon resonance (SPR) were employed to investigate the underlying mechanisms by which NEU4 promotes renal fibrosis." (PMID 39136142, 2024). "To investigate the role of NEU4 in the development of renal fibrosis, we used AAV to generate kidney‐specific NEU4 knockdown/overexpression mice by in situ injection." (PMID 39136142, 2024). "Kidney‐specific NEU4 knockdown and overexpression mice were generated by adeno‐associated virus (AAV) to characterize the role of NEU4 on the progression of renal fibrosis." (PMID 39136142, 2024). "HMF is screened as a novel NEU4 inhibitor, effectively attenuating renal fibrosis in a NEU4‐dependent manner." (PMID 39136142, 2024). "3,5,6,7,8,3ʹ,4ʹ‐Heptamethoxyflavone, a natural compound, is identified as a novel NEU4 inhibitor, effectively protecting mice from renal fibrosis in a NEU4‐dependent manner." (PMID 39136142, 2024). "Here, to address the existing scientific gray areas and loopholes in respect of the neuraminidases, this work aimed to study the role of NEU4 in renal fibrosis." (PMID 39136142, 2024). "Kidney‐specific NEU4 knockdown was sufficient to protect kidney from UUO‐ or folic acid‐induced renal fibrosis in mice and TGF‐β‐induced injury in TECs." (PMID 39136142, 2024). "In this study, we described the presence of NEU4 in TECs and revealed the significant involvement of NEU4 in renal fibrosis through the findings of in vivo, in vitro, and pharmacological investigations." (PMID 39136142, 2024). "We detected the NEU4 expression in patients with renal fibrosis, and in male mice subjected to unilateral ureteral obstruction (UUO) or administered folic acid (FA)." (PMID 39136142, 2024). "Although the influence of neuraminidases in other renal cell types such as glomerular podocytes and fibroblasts cannot be totally excluded in renal fibrosis, this study illuminates the significant role of tubular NEU4 in promoting renal fibrosis." (PMID 39136142, 2024). "Here, this study finds that NEU4 expression is markedly upregulated in mouse fibrotic kidneys induced by folic acid or unilateral ureter obstruction, and this elevation is observed in patients with renal fibrosis." (PMID 39136142, 2024). "In this work, we shown that NEU4 was significantly increased in patients with renal fibrosis, in mice undergoing unilateral ureteral obstruction (UUO) or receiving folic acid, and in human tubular epithelial HK‐2 cells or primary tubular epithelial cells (PTECs) stimulated with TGF‐β." (PMID 39136142, 2024). "Conversely, NEU4 overexpression exacerbates the progression of renal fibrosis." (PMID 39136142, 2024). "To determine whether the effect of HMF on renal fibrosis is depended on NEU4, we employed a NEU4 knockdown model." (PMID 39136142, 2024). "The expression of NEU4 in various diseases remains poorly understood, especially in renal fibrosis." (PMID 39136142, 2024). "In NEU4‐knockdown mice, treatment of HMF (50 mg kg−1) failed to further reduce kidney morphology, renal injury and renal fibrosis following UUO stimulation." (PMID 39136142, 2024). "To clarify the expression of NEU4 in kidney fibrosis, we first analyzed human kidney biopsies samples collected from patients with renal fibrosis (n = 5) and without renal fibrosis (noncancerous nephrectomy tissues, n = 4)." (PMID 39136142, 2024).
renal fibrosis (continued). "Immunohistochemistry (IHC) revealed that NEU4 protein levels were significantly higher in the tubules of kidney sections of patients with renal fibrosis than without renal fibrosis." (PMID 39136142, 2024). "To further examine the function of NEU4 in vivo, we deleted Neu4 in the left kidney of mouse by administration of AAV9‐miR30‐shRNA in situ, followed by a challenge of UUO for 10 days to induce renal fibrosis." (PMID 39136142, 2024). "Collectively, these results indicate that NEU4 interacts with YAP, inhibits YAP phosphorylation, promotes YAP transfer to the nucleus, and then activates YAP target genes expression, thereby contributing to renal fibrosis." (PMID 39136142, 2024).
Sepsis (1 paper, 2022). Sepsis is defined as life-threatening organ dysfunction caused by a dysregulated host response to infection. "Four subtypes of neutrophils were identified in the peripheral blood of sepsis, namely, the Neu1, Neu2, Neu3, and Neu4." (PMID 36304125, 2022).
Tay-Sachs disease (1 paper, 2010). GM2 gangliosidosis, variant B or Tay-Sachs disease is marked by accumulation of G2 gangliosides due to hexosaminidase A deficiency. "In the current work, we assessed whether Neu4 is the enzyme responsible in vivo for the metabolic bypass of the HexA defect in the mouse model of Tay-Sachs disease by studying mice with a double deficiency of Neu4 and HexA." (PMID 20862357, 2010). "Our data suggest that the Neu4 depletion exacerbates the disease in HexA knockout mice, supporting the view that Neu4 is one of the modifier genes in the mouse model of Tay-Sachs disease." (PMID 20862357, 2010). "Together, our data suggest that the Neu4 block exacerbates the disease in Hexa−/− mice, indicating that Neu4 is a modifier gene in the mouse model of Tay-Sachs disease, reducing the disease severity through the metabolic bypass." (PMID 20862357, 2010). "Our study demonstrates that the Neu4 block exacerbates the neurological phenotype the Hexa−/− mouse, supporting the view that Neu4 is a one of the modifier genes in the mouse model of Tay-Sachs disease." (PMID 20862357, 2010).
Tremor (1 paper, 2010). An unintentional, oscillating to-and-fro muscle movement about a joint axis. "However, neurological examination demonstrated that Neu4−/−;Hexa−/− mice showed tremor during locomotion, wide based stance, and increased spasticity in anterior and posterior limbs when held by the tail." (PMID 20862357, 2010).
cancer (9 papers, 2009 to 2024). A tumor composed of atypical neoplastic, often pleomorphic cells that invade other tissues. "NEU4 can reportedly regulate several cancer-associated glycans, such as sialyl Lewis A, sialyl Lewis X, and PSA-NCAM8,9, all three of which are highly expressed in colon cancers." (PMID 30700826, 2019). "Here we found that p73 and AP2 are able to activate NEU4, a neuraminidase gene, which removes the terminal sialic acid residues from cancer-associated glycans." (PMID 30700826, 2019). "Initially, we compared the status of Neu1/Neu2/Neu3/Neu4 in cancer and normal tissue specimens by immunohistochemistry." (PMID 29434218, 2018). "On the other hand, NEU4 is down-regulated in cancers, allowing for the increased expression of sialyl-Lewisx (and sialyl-Lewisa) carbohydrate structures, leading to increased tumor metastasis." (PMID 29912148, 2018). "Four mammalian NEU homologues are known so far—NEU1, NEU2, NEU3 and NEU4—of which NEU 1, 2 and 4 are downregulated in various cancers, resulting in sialoglycan accumulation in cancer cells." (PMID 30478534, 2019). "According to the TCGA data from the GEPIA web site, NEU4 is down-regulated in tumors compared to normal tissues in both colon (COAD) and rectal (READ) cancers." (PMID 30700826, 2019). "However, NEU4 expression and its link to cancer and inflammation are not well understood at this point." (PMID 29912148, 2018).
tumor (9 papers, 2016 to 2025). "In human high-grade serous ovarian cancer, elevated expression of the sialidase NEU4 is associated with tumor metastasis and poor survival, which in this tumor type might be linked to specific desialylation of N196 in EGFR." (PMID 40885395, 2025). "By comparing differentially expressed gene (DEG) profiles of tumor cells to those of the other cell types in the tumors, we discovered Neu4 and Gpr17 as tumor-specific markers." (PMID 41497446, 2025). "Neu4 and Gpr17 were expressed in >45% of the cells in the tumor cell cluster, <2% of the cells in the non-tumor cell clusters, with an average log2 fold change >4.5." (PMID 41497446, 2025). "Examination of Neu tumor cells revealed four clusters (Neu-1 to Neu-4) with well-defined characteristics to allow illustration of their hierarchical relationships." (PMID 32840210, 2020). "However, all treatments that reduced Nf1-OPG proliferation also exhibited decreased Neu4 and Gpr17 expression, suggesting similar effects of the various treatments on tumor cell content." (PMID 41497446, 2025). "Consequently, the preferential enrichment of Neu4 sgRNA in C2 suggests potential mechanisms contributing to increased cellular motility and elevated levels of tumor metastasis." (PMID 39605490, 2024). "Optical density score conferred higher Neu1, Neu3, and Neu4 positivity in the tumor tissues." (PMID 29434218, 2018). "Integrating NEU4 and NPL into the TSC1–mTORC1–sialylation axis further refines the mechanistic framework of PD-L1 hypersialylation–driven immune escape, highlighting a coordinated metabolic control of sialic acid turnover in tumor immune regulation." (PMID 41445741, 2025).
neurological disorders (1 paper, 2018). "Disruption of Neu3 and Neu4 genes has led to the generation of a mouse model revealing severe neurological disorders." (PMID 30359429, 2018).
NEU4 also shares sentences with these, for which no sentence is quoted: infection (2 papers); bladder cancer (1); breast carcinoma (1); cardiovascular diseases (1); galactosialidosis (1); gastric cancer (1); hepatocellular carcinoma (1); melanoma (1); metabolic disease (1); pilocytic astrocytoma (1); pulmonary disorders (1); sialidosis (1); ulcerative colitis disease (1); Ureteral obstruction (1).